MOG (myelin oligodendrocyte glycoprotein)
Diseases named in the same sentence as MOG in open-access papers (continued):
Sharing a sentence is not in itself a finding about the gene and the disease.
Leber hereditary optic neuropathy (3 papers, 2022 to 2024). Leber's hereditary optic neuropathy (LHON) is a mitochondrial neurodegenerative disease affecting the optic nerve and often characterized by sudden vision loss in young adult carriers. "Screening for autoimmune optic neuritis including testing for anti-myelin oligodendrocyte glycoprotein and aquaporin-4 antibodies and analysis of mitochondrial DNA mutations associated with Leber hereditary optic neuropathy yielded unremarkable results." (PMID 36254071, 2022). "Thus, Leber hereditary optic neuropathy at first presentation may be considered as a differential for MOG-ON, but the presence of pain and the more rapid visual loss in MOG-ON forms a key distinction." (PMID 38783085, 2024). "Interestingly, there is one reported case of acute MOG-ON occurring in a known Leber hereditary optic neuropathy carrier." (PMID 38783085, 2024). "The patient tested negative for aquaporin-4 and myelin oligodendrocyte glycoprotein antibodies and Leber hereditary optic neuropathy-associated gene mutations." (PMID 36254071, 2022). "Recent reports of recessive optic atrophy in MOG-Ab + ON, i.e., no changes in visual function, such as visual field, but thinning of RNFL, further support this hypothesis." (PMID 35360549, 2022).
Leukoencephalopathy (3 papers, 2010 to 2021). This term describes abnormality of the white matter of the cerebrum resulting from damage to the myelin sheaths of nerve cells. "For example, in anti-MOG-associated leukoencephalopathy and brainstem encephalitis, punctate and curvilinear gadolinium enhancement (PCGE) has been reported." (PMID 33391163, 2020). "Although the patient had clinically improved 20 weeks after the first visit, the MRI scan showed a deterioration of leukoencephalopathy paralleled by a sharp increase of OD values for MOG IgG antibodies." (PMID 21083890, 2010).
nervous (3 papers, 2020 to 2025). "Myelin oligodendrocyte glycoprotein (MOG) antibody-associated disease (MOGAD) is the most recently defined inflammatory demyelinating disease of the central nervous system (CNS)." (PMID 35785363, 2022).
neuropathy (3 papers, 2022 to 2024). A disorder affecting the nervous system that manifests with pain, tingling, numbness, and/or muscle weakness. "We present a patient who had clinical, neurophysiological, radiological, and biochemical findings that support the diagnosis of CCPD (multifocal motor neuropathy and cord lesion) with MOG antibodies." (PMID 36601183, 2022).
neurosyphilis (3 papers, 2023 to 2025). Infection of the brain or spinal cord by Treponema pallidum. "In patients with neurosyphilis, it is strongly recommended to perform testing for MOG antibody along with other brain disease antibodies." (PMID 37859651, 2023).
Obesity (3 papers, 2016 to 2023). Accumulation of substantial excess body fat. "A recent study showed that IL-6 was required for obesity-associated Th17 cell expansion during induction of EAE with myelin oligodendrocyte glycoprotein 35–55." (PMID 36982669, 2023). "In vitro, Peroxisome Proliferator-Activated Receptor gamma (PPAR-γ), a regulator of adipocyte differentiation implicated in obesity, is strongly upregulated following demyelination mediated by antibodies directed against the Myelin Oligodendrocyte Glycoprotein (MOG) in the presence of complement." (PMID 27721574, 2016).
ovarian teratoma (3 papers, 2021 to 2023). A non-seminomatous germ cell tumor arising from the ovary. "An association of MOG-EM with ovarian teratoma has been previously observed by us and others in 2/77 patients from two cohorts." (PMID 33078290, 2021). "This patient developed two rather mild episodes of MOG-IgG-associated ON 11 and 16 months after diagnosis of an ovarian teratoma, which expressed MOG and other myelin proteins." (PMID 33078290, 2021). "GFAP-IgG antibodies can coexist with anti-NMDAR-IgG, MOG-IgG, and Yo antibodies, but the proportion of concurrent ovarian teratomas was found to be significantly lower than that noted in previous research." (PMID 36552122, 2022). "We report on a patient with oligosymptomatic MOG-EM emerging several months after detection and resection of an ovarian teratoma." (PMID 33078290, 2021).
Parkinson disease (3 papers, 2014 to 2024). A progressive degenerative disorder of the central nervous system characterized by loss of dopamine producing neurons in the substantia nigra and the presence of Lewy bodies in the substantia nigra and locus coeruleus. "The genes that directly interact with PLLP are involved in cell-to-cell communication and neurological-related diseases, such as the completion and maintenance of myelin sheath (MOG), the ion transporter (SLC31A2) (Schweigel-Röntgen, 2014), and Parkinson’s disease (DBNDD2)." (PMID 33304381, 2020).
Respiratory insufficiency (3 papers, 2016 to 2021). "Cases 1 and 2 illustrate that the prognosis differs widely among MOG-IgG-positive patients: while brainstem encephalitis led to respiratory insufficiency in both patients, it was fatal in the former case and remitted almost completely in the latter." (PMID 27802825, 2016).
systemic sclerosis (3 papers, 2022 to 2024). A chronic disorder, possibly autoimmune, marked by excessive production of collagen which results in hardening and thickening of body tissues. "In systemic sclerosis (SSc), myelin basic protein (MBP) and myelin oligodendrocyte glycoprotein (MOG) can act as potential targets within the central nervous system (CNS)." (PMID 39734406, 2024).
Aphasia (2 papers, 2023 to 2025). An acquired language impairment of some or all of the abilities to produce or comprehend speech and to read or write. "To date, only three cases of MOG-IgG-associated AHEM have been documented, and the symptoms presented by the patient, including altered consciousness, aphasia, and hemiparesis, were previously identified as manifestations of MOG-IgG-associated AHEM." (PMID 37835890, 2023).
astrocytoma (2 papers, 2021 to 2022). "Astrocytoma should be considered as a high-risk factor for MOG-EM." (PMID 36221336, 2022). "MOG-EM might be associated with astrocytoma or its treatment." (PMID 36221336, 2022). "In previous studies, polyclonal antibody has been found in cancer patients, such as aquaporin-4 and MOG-IgG in astrocytoma patients." (PMID 36221336, 2022). "The clinical symptoms and MRI are unable to provide sufficient evidence for us to differentiate astrocytoma recurrence from MOG-EM." (PMID 36221336, 2022). "But this patient of our report developed MOG-EM after the astrocytoma." (PMID 36221336, 2022). "But the case of our study finds that astrocytoma can coexist with MOG-EM." (PMID 36221336, 2022). "What’s more, it reminds us that the pathogenesis of MOG-EM might be related to astrocytoma." (PMID 36221336, 2022). "Therefore, the diagnosis of MOG-EM and astrocytoma is clear." (PMID 36221336, 2022). "What’s more, MOG-EM might be secondary to astrocytoma or its treatment." (PMID 36221336, 2022). "However, the correlation between MOG-EM and astrocytoma remains unclear." (PMID 36221336, 2022). "This astrocytoma patient was diagnosed with MOG-EM according to comprehensive evidence, including MRI, visual evoked potential (VEP), serum myelin oligodendrocyte glycoprotein antibody (MOG-IgG), and therapeutic effect." (PMID 36221336, 2022). "Our case reports a 49-year-old woman with medical history of astrocytoma (WHO grade II, isocitrate dehydrogenase 1) for more than 4 years who was recently diagnosed with MOG-EM." (PMID 36221336, 2022). "We observed that most cells are GFAP+ astrocytoma cells, as well as relatively low proportions of PTRPC+ immune cells and MOG+ oligodendrocytes in this tumor." (PMID 34805184, 2021).
Blindness (2 papers, 2013 to 2021). Blindness is the condition of lacking visual perception defined as a profound reduction in visual perception. "The thickness of the MOG is significantly increased in patients with early-onset blindness, which is considered to be the result of compensation." (PMID 33972462, 2021).
central nervous system infection (2 papers, 2019 to 2023). "We report three patients with HIV infection and myelin oligodendrocyte glycoprotein (MOG) antibodies in the setting of other central nervous system infections." (PMID 37845760, 2023).
collagen disease (2 papers, 2024 to 2025). "The current five-fold increased risk of SIEs in AQP4+ patients, compared to the MOG+ group, may likely partly be related to co-morbid rheumatic disease, and associated treatments, which was absent in MOG+ patients." (PMID 38256489, 2024).
cranial nerve ( (2 papers, 2023 to 2024). "However, in our study, the MOG-seropositive ADEM children were found to present fewer seizures and lower rates of cranial nerve (III–XII) palsy than seronegative children." (PMID 37274199, 2023).
dementia (2 papers, 2010 to 2014). Loss of intellectual abilities interfering with an individual's social and occupational functions. "MOG immunopositive HAND patients performed significantly worse on the HIV dementia scale and showed higher viral load in CSF." (PMID 21083890, 2010).
erectile dysfunction (2 papers, 2018 to 2019). Persistent or recurrent inability to achieve or to maintain an erection during sexual activity. "Among men, erectile dysfunction more commonly occurred in patients with MOG-Ab disease than those with AQP4-Ab disease (6 patients [46%] vs 2 patients [29%]; P < .001)." (PMID 31596489, 2019). "This difference persisted to the increased presence of erectile dysfunction at last follow-up in patients with MOG-Ab disease." (PMID 31596489, 2019). "In the recovery analysis, erectile dysfunction occurred more commonly in patients with MOG-Ab disease than in those with AQP4-Ab disease (9 men [41%] vs 1 man [8%]; P = .52)." (PMID 31596489, 2019).
Hepatitis (2 papers, 2024 to 2025). Inflammation of the liver. "In fact, cross-reactivity between HBV surface antigen and MOG peptides has been reported previously, and it has been suggested that syphilis infection can lead to Epstein–Barr virus reactivation and hepatitis." (PMID 39295869, 2024).
hypothyroidism (2 papers, 2017 to 2023). Abnormally low levels of thyroid hormone. "In addition, one AQP4-ON patient and one MOG-ON patient were positive for antinuclear antibodies (ANA), and one MOG-ON patient had hypothyroidism." (PMID 36969199, 2023). "In accordance with our hypothesis, transitory hypothyroidism during demyelination, followed by T3/T4 pulses to favor oligodendrocyte maturation, increased Myelin Basic Protein (MBP) and Myelin Oligodendrocyte (MOG), two markers of maturing oligodendrocytes, in the corpus callosum and septum." (PMID 28875931, 2017).
mental disorder (2 papers, 2022 to 2025). A disease that has its basis in the disruption of mental process. "Although MOG antibodies have also been described in a small number of patients with other conditions, including mental disorders, their prevalence and clinical specificity in patients with isolated psychotic symptoms remain unclear." (PMID 40757033, 2025). "Therefore, patients that exhibit psychiatric disorders or seizures as well as demyelination and atypical brain lesions, especially infratentorial lesions, should be screened for MOG-IgG and NMDAR-IgG together." (PMID 36009058, 2022).
multiple system atrophy (2 papers, 2022 to 2024). Multiple system atrophy (MSA) is a neurodegenerative disorder characterized by autonomic failure (cardiovascular and/or urinary), parkinsonism, cerebellar impairment and corticospinal signs with a median survival of 6-9 years. "They observed that these MOG+ EVs obtained from patients with multiple system atrophy (MSA), a frequent PD-mimic disease, contained higher levels of α-synuclein compared to both PD patients and control subjects." (PMID 38898538, 2024).
Opsoclonus (2 papers, 2025 to 2026). "While both glutamic acid decarboxylase (GAD) and myelin oligodendrocyte glycoprotein (MOG) antibodies have individually been reported to be associated with opsoclonus, reports of a combination of these two in a patient with gastric cancer with isolated reversible opsoclonus are scarce." (PMID 41728525, 2026).
palsy (2 papers, 2023 to 2026). A general term most often used to describe severe or complete loss of muscle strength due to motor system disease from the level of the cerebral cortex to the muscle fiber. "MOG-seropositive ADEM children presented with significantly lower rates of seizures (P = 0.038) and cranial nerve (III–XII) palsy (P = 0.003)." (PMID 37274199, 2023).
psoriasis (2 papers, 2022 to 2025). An autoimmune condition characterized by red, well-delineated plaques with silvery scales that are usually on the extensor surfaces and scalp. "Overall, our data indicated that CMTM4 regulates IL-17A signaling in vivo and mediates IMQ-induced psoriasis, while it had only a limited role in MOG-induced EAE." (PMID 36271145, 2022). "Moreover, MOG drives Th17/Th1 cells to produce IL-17A and TNF-α, which may have a potential impact on psoriasis." (PMID 40564099, 2025).
radiculitis (2 papers, 2021 to 2022). An inflammatory process affecting a nerve root. "One patient with VZV infection and radiculitis had a borderline MOG-IgG positive titer of 1:160." (PMID 34737756, 2021).
Retinal atrophy (2 papers, 2019). A nonspecific term denoting wasting, especially as a result of degeneration, of the retinal pigment epithelium (RPE) and neurosensory retinal cells. "Additionally, our study lacks magnetic resonance imaging data on optic nerve lesion lengths and lesion volumes of the afferent visual system as well as whole-brain lesion volume to further evaluate subclinical retinal atrophy in MOG-IgG-associated diseases." (PMID 31345223, 2019).
Sepsis (2 papers, 2020 to 2021). Sepsis is defined as life-threatening organ dysfunction caused by a dysregulated host response to infection. "Finally, to determine whether the sepsis-induced loss of MOG-specific CD4 T cell precursors is causal in the reduced disease severity of EAE mice, the same 2D2 transfer and surgery groups were used as before and disease progression was monitored." (PMID 33191915, 2020). "The reduced number of MOG-specific CD4 T cell precursors seems to be a factor at a time proximal to sepsis induction." (PMID 33191915, 2020). "Additionally, we observed a numerical recovery of MOG-specific CD4 T cells with time after sepsis in some animals." (PMID 33191915, 2020). "Sepsis reduces the number of cytokine-producing MOG-specific CD4 T cells in the CNS." (PMID 33191915, 2020). "Serum available from the acute EHEC sepsis phase was retrospectively tested and negative for MOG‐IgG." (PMID 33047894, 2021). "To further delineate the contributions of the sepsis influence directly on CD4 T cells or their environment, we utilized an adoptive transfer system wherein naive MOG-specific, TCR-transgenic 2D2 CD4 T cells were transferred into congenically distinct recipient mice." (PMID 33191915, 2020). "Sepsis reduces the number of MOG-specific CD4 T cells but not their capacity to proliferate." (PMID 33191915, 2020). "With these tools, we established that sepsis diminishes the number of MOG-specific CD4 T cell precursors but does not alter capacity of the surviving cells to proliferate (either by intrinsic or extrinsic mechanisms) or promote disease if numerically bolstered." (PMID 33191915, 2020).
sexual dysfunction (2 papers, 2021 to 2023). Disturbances in sexual desire and the psychophysiologic changes that characterize the sexual response cycle and cause marked distress and interpersonal difficulty. "Conus involvement (Figure 2A4) can be a clue to MOG antibody-associated disorder and neurogenic bowel, bladder, and/or sexual dysfunction are common in conjunction with this." (PMID 34305787, 2021). "Whereas persistent severe motor impairment after acute myelitis is more suggestive of AQP4-IgG-positive NMOSD than of MOG-EM/MOGAD, persisting sphincter disturbance/sexual dysfunction is more commonly seen in MOG-EM/MOGAD, as the latter disorder more often affects the conus than does NMOSD." (PMID 37022481, 2023).
temporal lobe epilepsy (2 papers, 2021 to 2023). A localization-related (focal) form of epilepsy characterized by recurrent seizures that arise from foci within the temporal lobe, most commonly from its mesial aspect. "Similar to this study, increased expression of MOG, PLP1, ABCA2, FA2H, TF, ASPA was demonstrated in high-spiking regions of cortical areas of temporal lobe epilepsy patients." (PMID 34301297, 2021).
upper respiratory tract infection (2 papers, 2016 to 2017). "Of note, 45% of MOG-Ab positive cases had infectious and flu-like prodromes, including fever, gastrointestinal symptoms, upper respiratory tract infection, and dental infection." (PMID 29063242, 2017).
acute transverse myelitis (1 paper, 2025). Acute transverse myelitis (ATM) is an inflammatory demyelinating disorder of the spinal cord that can be either idiopathic (IATM) or secondary to a known cause (SATM). "MRI demonstrated a central thoracic cord lesion at T11, consistent with acute transverse myelitis, while serum AQP4 and MOG antibodies were negative." (PMID 41441534, 2025).
alopecia (1 paper, 2024). Hair loss usually from the scalp. "A MOG-associated model of alopecia has previously been described." (PMID 39450167, 2024).
Apathy (1 paper, 2023). Apathy is a quantitative reduction of interest, motivation and the initiation and persistence of goal-directed behavior, where often the accompanying emotions, thoughts, and social interactions are also diminished. "These two patients developed apathy, seizures, and memory loss during the recovery period; a reexamination of the head MRI revealed new multifocal white matter lesions, and serum MOG antibodies were detected." (PMID 37153594, 2023).
autism (1 paper, 2015). Persistent deficits in social interaction and communication and interaction as well as a markedly restricted repertoire of activity and interest as well as repetitive patterns of behavior. "BTN and MOG share the same behavior in MS experimental models, and MOG/BTN cross-reactive antibodies have been found in MS, in autism and in coronary heart disease (CHD; Riccio, 2004)." (PMID 25694551, 2015).
B-cell lymphomas (1 paper, 2025). "Originally developed for the treatment of B-cell lymphomas, RTX has gained broad application in autoimmune demyelinating diseases such as MS, NMOSD, and myelin oligodendrocyte glycoprotein-associated disease." (PMID 41181092, 2025).
bowel dysfunction (1 paper, 2024). Any disease in which the causes of the disease is a perturbation of the lower digestive tract leading to its dysfunction. "Among the others, two-thirds of the AQP4+ patients had reported symptoms associated with urinary tract and/or bowel dysfunction, while this was rarer (less than one-third) in MOG+ and double-seronegative patients." (PMID 38256489, 2024).
cerebral infarction (1 paper, 2024). An ischemic condition of the brain, producing a persistent focal neurological deficit in the area of distribution of the cerebral arteries. "In order to discuss the clinical and MRI features, diagnosis, and prevention of myelin oligodendrocyte glycoprotein antibody-associated disease (MOGAD), we reported an adult case of MOG antibody-related disease misdiagnosed as cerebral infarction." (PMID 39220233, 2024).
channelopathies (1 paper, 2011). "MOG is not a target antigen in "AQP4 channelopathies", raising the question of whether MOG-IgG positive NMO and HR-NMO patients share a possible disease overlap with MOG-IgG positive ADEM." (PMID 22204662, 2011).